UBE2W (ubiquitin conjugating enzyme E2 W)
Description:
Accepts ubiquitin from the E1 complex and catalyzes its covalent attachment to other proteins. Specifically monoubiquitinates the N-terminus of various substrates, including ATXN3, MAPT/TAU, POLR2H/RPB8 and STUB1/CHIP, by recognizing backbone atoms of disordered N-termini. Involved in degradation of misfolded chaperone substrates by mediating monoubiquitination of STUB1/CHIP, leading to recruitment of ATXN3 to monoubiquitinated STUB1/CHIP, and restriction of the length of ubiquitin chain attached to STUB1/CHIP substrates by ATXN3. After UV irradiation, but not after mitomycin-C (MMC) treatment, acts as a specific E2 ubiquitin-conjugating enzyme for the Fanconi anemia complex by associating with E3 ubiquitin-protein ligase FANCL and catalyzing monoubiquitination of FANCD2, a key step in the DNA damage pathway. In vitro catalyzes 'Lys-11'-linked polyubiquitination. UBE2W-catalyzed ubiquitination also occurs in the presence of inactive RING/U-box type E3s, i.e. lacking the active site cysteine residues to form thioester bonds with ubiquitin, or even in the absence of E3, albeit at a slower rate.
Synonyms: UBC-16; UBC16; FLJ11011
Tractability: PROTAC: UniProt records ubiquitination sites on it; ubiquitination databases record sites on it.
Gene: Protein-coding gene on chromosome 8 (73,780,097 to 73,878,910, reverse strand). Ensembl gene ENSG00000104343.
Subcellular location: Nucleus
Subcellular location (Human Protein Atlas): Nucleoli
Pathways (Reactome):
Immune System: Antigen processing: Ubiquitination & Proteasome degradation
Metabolism of proteins: Synthesis of active ubiquitin: roles of E1 and E2 enzymes
Gene Ontology:
Molecular function: protein binding; ubiquitin conjugating enzyme activity; ubiquitin protein ligase binding; ubiquitin-protein transferase activity
Biological process: antiviral innate immune response; negative regulation of TORC1 signaling; proteasome-mediated ubiquitin-dependent protein catabolic process; protein K11-linked ubiquitination; protein monoubiquitination; cellular response to misfolded protein; protein polyubiquitination; protein quality control for misfolded or incompletely synthesized proteins; protein ubiquitination
Cellular component: nucleus; cytoplasm; nucleoplasm
Genetic constraint (gnomAD): Loss-of-function variants: 10 observed, 12.56 expected, observed/expected ratio (o/e) 0.8, 90% interval 0.49 to 1.35. The upper end of that interval is the gene's LOEUF score, 1.35, which puts it in group 5 of 6, group 1 being the genes least tolerant of losing a copy. Missense variants: 63 observed, 125.75 expected, observed/expected ratio (o/e) 0.5, 90% interval 0.41 to 0.62. Synonymous variants: 39 observed, 41.63 expected, observed/expected ratio (o/e) 0.94, 90% interval 0.72 to 1.22.
Homologues: Orthologues: chimpanzee UBE2W (100% identical), guinea pig UBE2W (100% identical), pig UBE2W (100% identical), rabbit UBE2W (100% identical), rat Ube2w (100% identical), mouse Ube2w (99% identical), macaque UBE2W (98% identical), dog UBE2W (97% identical), zebrafish ube2wb (97% identical), rat Ube2w (97% identical), tropical clawed frog ube2w (96% identical), zebrafish ube2wa (93% identical), and 2 more. Paralogues in human: UBE2B (36% identical), UBE2R2 (36% identical), UBE2A (35% identical), CDC34 (32% identical), UBE2T (31% identical), UBE2Z (31% identical), UBE2N (30% identical), UBE2G1 (29% identical), UBE2C (28% identical), UBE2I (28% identical), UBE2G2 (28% identical), UBE2K (26% identical), and 12 more.
Diseases named in the same sentence as UBE2W in open-access papers:
UBE2W is named in the same sentence as 30 diseases in open-access papers, as found by Europe PMC text mining. Sharing a sentence is not in itself a finding about the gene and the disease. The quoted sentences say what the papers report.
anaemia (1 paper, 2013). "Ube2W has been shown to be responsible for the mono-ubiquitylation of BRCA1 (breast cancer early-onset 1), Fanconi's anaemia proteins FANCL (Fanconi's anaemia, complementation group L) and FANCD2 (Fanconi's anaemia, complementation group D2) and CHIP." (PMID 23560854, 2013).
Atrophy (1 paper, 2024). Any weakening or degeneration, especially through lack of use. "Therefore, the two-step mechanism of UBE2W and UBE2N/V could play an important role in regulating the function of MuRF1 during denervation-induced muscle atrophy." (PMID 38283190, 2024).
breast carcinoma (1 paper, 2021). "We observed that UBE2W expression levels were significantly positively associated with tumor purity (r = 0.176, P = 2.23e-08) in breast cancer." (PMID 33931024, 2021). "Taken together, these results strongly demonstrated the UBE2W gene was abnormally regulated in multiple cancers than matched normal tissues, especially in breast cancer." (PMID 33931024, 2021). "Several datasets showed high expression levels of UBE2W was significantly in cancer samples verse in normal samples, including breast cancer (BRCA), head and neck cancers (HNSC), lymphoma, colorectal cancer, melanoma." (PMID 33931024, 2021). "Oncomine datasets shown UBE2W expression was upregulated in breast cancer, colorectal cancer, head and neck cancer, lung cancer." (PMID 33931024, 2021). "Results showed that UBE2W expression was positively correlated to all those genes in breast cancer, especially in the luminal A subtype." (PMID 33931024, 2021). "In brief, those results prompt that UBE2W is a prognostic biomarker for breast cancer." (PMID 33931024, 2021). "The expression of UBE2W was absolutely higher in breast cancer than normal tissues similarly." (PMID 33931024, 2021). "In this study, UBE2W expression was positively related to the expression of DNMTs in breast cancer." (PMID 33931024, 2021). "In general, UBE2W has an impotent prognostic value in various tumors, especially in breast cancer." (PMID 33931024, 2021). "All those results demonstrated that a high expression level of UBE2W may induce poor prognosis survival through promoting the endocrine therapy resistance in breast cancer, especially in the subtype of luminal A." (PMID 33931024, 2021). "Genomic Profiles of UBE2W in breast cancer (BRCA) were accessed in cBioPortal (v3.5.0)." (PMID 33931024, 2021). "High expression of UBE2W may promote the tumor immunosuppression and metastasis, induce endocrine therapy resistance and deteriorate outcomes of patients with breast cancer." (PMID 33931024, 2021). "And UBE2W may play a crucial role in the progress of breast cancer." (PMID 33931024, 2021). "In this study, we found that UBE2W expression was closely related to the expression level of BRCA1/2 and 5 MMR genes in breast cancer." (PMID 33931024, 2021).
depression (1 paper, 2022). "In this research, UBE2W and UBE2D1 were detected to be down-regulated in MDD adolescents, indicating down-regulation the in immune function of major depression." (PMID 35328018, 2022). "Although previous studies have not identified UBE2W and UBE2D1 to be closely correlated with depression, transcriptome analyses have discovered that depression is linked to a range of biological processes which may be involved in inflammation and immune activation." (PMID 35328018, 2022).
esophageal squamous cell carcinoma (1 paper, 2021). Esophageal squamous cell carcinoma (ESCC) is a type of esophageal carcinoma (EC) that can affect any part of the esophagus, but is usually located in the upper or middle third. "Consistent with the results of PrognoScan analysis, a higher expression level of UBE2W was correlated with better prognostic in lung cancer, gastric cancer, KIRC, and esophageal squamous cell carcinoma." (PMID 33931024, 2021).
Huntington disease (1 paper, 2022). Huntington disease (HD) is a rare neurodegenerative disorder of the central nervous system characterized by unwanted choreatic movements, behavioral and psychiatric disturbances and dementia. "Previous studies have found that UBE2W expression is significantly correlated with the immune environment, and it is associated with neurodegenerative diseases and Huntington’s disease." (PMID 35328018, 2022).
metastatic tumors (1 paper, 2021). "Compare the mRNA expression level of UBE2W in the metastatic tumors to the primary tumors, a rising trend was detected." (PMID 33931024, 2021).
cancer (3 papers, 2021 to 2023). A tumor composed of atypical neoplastic, often pleomorphic cells that invade other tissues. "In the present study, we primarily focus on the association between UBE2W expression and patients’ prognosis in different cancer types." (PMID 33931024, 2021). "An integrated analysis that we performed reveals that UBE2W was a potential oncogenic gene with prognostic value in BRCA, which is the first study of the UBE2W gene with cancer." (PMID 33931024, 2021). "In the present research, we verified different expression levels of UBE2W in normal and tumor from multi-omics data integration and analysis in specific cancer." (PMID 33931024, 2021). "Therefore, our study provides clues to shed light on the potential effects of UBE2W in cancer research." (PMID 33931024, 2021). "Additionally, the gene targets of these miRNAs included several cancer driver genes including ZNF704 (targeted by ten miRNAs), MMP16 (targeted by eight miRNAs), and KCNN3, POU2F1, ADARB1, MPZL1, RUNX1T1, UBE2W, and DYRK1A genes (targeted by seven miRNAs)." (PMID 37685851, 2023). "However, the roles of UBE2W in human pan-cancer has not been identified." (PMID 33931024, 2021).
tumor (1 paper, 2021). "In this study, we found that UBE2W expression was associated with tumor infiltration immune cells in BRCA." (PMID 33931024, 2021). "Firstly, the difference mRNA expression level of UBE2W between tumor and normal was performed in various public datasets." (PMID 33931024, 2021). "Secondly, we found UBE2W exhibited a significantly higher expression profile in BRCA tumor tissues than in normal tissues." (PMID 33931024, 2021). "We investigated UBE2W expression in the Oncomine database, the Tumor Immune Estimation Resource (TIMER), TNMplot database." (PMID 33931024, 2021). "UBE2W might promote tumor metastasis and the resistance of endocrine therapy though influencing the process of DNA repair and DNA methyltransferase, inducing the tumor immunosuppression." (PMID 33931024, 2021). "A high expression level of UBE2W may promote tumor metastasis in BRCA." (PMID 33931024, 2021). "Thus, we speculated UBE2W may be involved in the tumor immune microenvironment." (PMID 33931024, 2021).
UBE2W also shares sentences with these, for which no sentence is quoted: adrenocortical carcinoma (1 paper); cholangiocarcinoma (1); colon adenocarcinoma (1); colorectal cancer (1); COVID-19 (1); esophageal carcinoma (1); Fanconi's anaemia (1); gastric cancer (1); head and neck cancer (1); head and neck tumor (1); lung adenocarcinoma (1); lung carcinoma (1); lung squamous cell carcinoma (1); lymphoma (1); melanoma (1); neurodegenerative disease (1); ovarian serous cystadenocarcinoma (1); rectal adenocarcinoma (1); sarcoma (1); stomach adenocarcinoma (1); uterine carcinosarcoma (1).